CD22 (CD22 molecule)
Diseases named in the same sentence as CD22 in open-access papers (continued):
Sharing a sentence is not in itself a finding about the gene and the disease.
hairy cell leukemia (47 papers, 2003 to 2025). Hairy cell leukemia (HCL) is a rare type of leukemia in which abnormal B-lymphocytes are present in the bone marrow, spleen and peripheral blood. "Recently, a PE-based immunotoxin Moxetumomab Pasudotox (Lumoxiti), targeting CD22, has been approved for the treatment of patients with hairy cell leukemia." (PMID 34067057, 2021). "In a clinical trial, Moxetumomab pasudotox, an anti-CD22 immunotoxin agent, was used for the treatment of adults with relapsed or refractory hairy cell leukemia (HCL)." (PMID 34960243, 2021). "For example, the recently approved moxetumomab pasudotox combine the PE38 Pseudomonas endotoxin with and anti-CD22 scFv, and it is suitable for the treatment of hairy cell leukemia." (PMID 32859066, 2020). "Recently, a PE-based immunotoxin, targeting CD22, was approved for treating patients with hairy cell leukemia." (PMID 32957689, 2020). "The FDA recently approved Lumoxiti, a CD22-targeting recombinant immunotoxin using Pseudomonas exotoxin A, as a treatment for patients with relapsed or refractory hairy cell leukemia that have received at least two prior systemic therapies." (PMID 32575752, 2020). "The U.S. Food and Drug Administration (FDA) recently approved Lumoxiti, a CD22-targeting immunotoxin, as a treatment for patients with hairy cell leukemia." (PMID 32575752, 2020). "A literature search was conducted in the PubMed database from inception to January 2019, using the following terms: moxetumomab, hairy cell leukemia, relapsed/refractory hairy cell leukemia, immunotoxin, and CD22." (PMID 31134324, 2019). "In particular, there is evidence of activity in hematological tumor types, for example, with the anti-CD22 immunotoxin RFB4(dsFv)-PE38 (BL22) in hairy cell leukemia (HCL)." (PMID 23443108, 2012). "Nonetheless the CD22-pseudomonas exotoxin fusion protein CD22-PE is one of the most effective treatments for hairy cell leukaemia." (PMID 12888809, 2003). "Hairy cell leukemia (HCL) is a rare mature B-cell malignancy with high CD22 expression." (PMID 33627164, 2021). "CD22 antigen is found on the surface of hairy cell leukemia (HCL) cells." (PMID 22190975, 2011). "CD22 is expressed on the surface of various malignant B cells, including hairy cell leukemia (HCL), the current approved use of Lumoxiti." (PMID 37766309, 2023). "Hairy cell leukemia (HCL) is a purine analog-responsive B-cell malignancy containing the BRAF V600E mutation, expressing CD22, CD11c, CD103, tartrate resistant acid phosphatase (TRAP) CD25, CD123, and annexin 1A." (PMID 32040482, 2020). "This is a pivotal, multicenter, open-label study of moxetumomab pasudotox, a recombinant CD22-targeting immunotoxin, in hairy cell leukemia (HCL), a rare B cell malignancy with high CD22 expression." (PMID 30030507, 2018). "Lumoxiti comprising of a CD22-targeting scFv domain and a truncated Pseudomonas exotoxin A domain has been approved by FDA for relapsed or refractory hairy cell leukemia." (PMID 36435809, 2022). "Another drug, Moxetumomab Pasudotox, which combines anti-CD22 with PE38, a fragment of Pseudomonas exotoxin A, has shown efficacy in patients with hairy cell leukemia (HCL)." (PMID 30323814, 2018). "Patients with hairy cell leukemia (HCL), a rare B cell malignancy characterized by high CD22 expression, typically present with pancytopenia and increased susceptibility to infection." (PMID 30030507, 2018). "For treatment of refractory Hairy Cell Leukemia (HCL), Moxe targeting CD22 achieved 75% objective response rates in a pivotal, multicenter, open-label trial of 80 patients." (PMID 30577664, 2018). "Moxetumomab pasudotox is an anti-CD22 immunotoxin consisting of an Fv as the targeting moiety fused to Pseudomonas exotoxin-A, which is being investigated in Phase III clinical trials for hairy cell leukemia (HCL)." (PMID 24738036, 2014).
hairy cell leukemia (continued). "Many toxin-based therapies are under clinical trials, but Moxetumomab pasudotox, composed of an anti-CD22 antibody fused to a 38 kDa portion of the Pseudomonas exotoxin A, is one of the few approved immunotoxins by the FDA, in this case for the treatment of hairy-cell leukemia." (PMID 35532120, 2022). "A CD22-targeting immunotoxin, Moxetumomab pasudotox (Moxe, CAT-8015/HA22), was developed for treating hairy cell leukemia (HCL)." (PMID 34827170, 2021). "Similarly, a hydrazone linker is also used to connect anti-CD22 mAbs to cytotoxins such as calicheamicin (inotuzumab ozogamicin) and pasudotox-tdfk (moxetumomab pasudotox-tdfk) for treatment of CD22-positive ALL and relapsed hairy cell leukemia in clinics, respectively." (PMID 36354547, 2022). "CD22 is also expressed by most B cell malignancies, including leukemic blasts in > 90% patients with B cell ALL, as well as chronic lymphocytic leukemia (CLL), NHL, and hairy cell leukemia (HCL)." (PMID 31500657, 2019). "The first CD22-targeting rIT BL22 (CAT-3888) is active against B-cell non-Hodgkin lymphoma (B-NHL) cell lines in vitro and achieves an objective response rate of 81% in patients with hairy cell leukemia (HCL)." (PMID 28423727, 2017). "Moxetumomab Pasudotox, which has been recently marketed, is developed for the treatment of R/R Hairy Cell Leukemia (HCL) which has failed to respond to more than two prior treatments, with CD22 as its primary target." (PMID 40211406, 2025). "Several ADCs targeting CD22 have been developed, including inotuzumab ozogamicin, FDA approved for use in relapsed/refractory B-ALL, and moxetumomab pasudotox-tdfk, approved for use in patients with R/R hairy cell leukemia (HCL) after two prior lines of therapy." (PMID 37296844, 2023). "CD22 is an inhibitory co-receptor of the B-cell receptor that is expressed on the surface of normal B lymphocytes and also many malignant B cells including chronic B-lymphocytic cells (B-CLL), B-lymphoma cells such as Burkitt’s lymphoma, and hairy cell leukemia (HCL)." (PMID 34976821, 2021).
B-cell acute lymphoblastic leukemia (40 papers, 2019 to 2026). A neoplasm of lymphoblasts committed to the B-cell lineage, typically composed of small to medium-sized blast cells. "CD22 encodes for a surface molecule and is known to be expressed by most blasts of B-cell acute lymphoblastic leukemia." (PMID 34202213, 2021). "Bicistronic CAR T cells targeting CD19 and CD22 exhibit clinical activity and low toxicity in pediatric and young adult patients with B cell acute lymphoblastic leukemia, with relapses associated with limited CAR T cell persistence." (PMID 34642489, 2021). "A phase I trial of CAR-T cells with CD19 and CD22 in young patients with relapsed or refractory B-cell acute lymphoblastic leukemia demonstrated controlled toxicity, with 5 out of 12 patients showing complete remission." (PMID 38919533, 2024). "The aim of this study was to assess the relationship between culture conditions, specifically culture pH, and the growth kinetics and properties of CD22 CAR T-cells used for the treatment of pediatric B-cell acute lymphoblastic leukemia." (PMID 38659083, 2024). "Inotuzumab ozogamicin, a humanized CD-22–targeting ADCs, is utilized as a monotherapy in the treatment of adult patients with relapsed/refractory B-cell acute lymphoblastic leukemia." (PMID 38665947, 2024). "In a clinical trial, CD22 CAR-T cells demonstrated an 80% response rate (24/30 patients) in the treatment of refractory or relapsed B-cell acute lymphoblastic leukemia, providing a valuable window of time for subsequent hematopoietic stem cell transplantation." (PMID 39995821, 2024). "A phase-1 clinical trial executed on LBCL patients using bispecific CAR T cells indicated that CD19/CD22 CAR T-cells exhibited favorable results in B-cell acute lymphoblastic leukemia patients with 82% MRD-CR and in LBCL patients with 62% ORR." (PMID 39312080, 2024). "This case series reports durable remissions in 2 patients with relapsed/refractory B-cell acute lymphoblastic leukemia treated with allogeneic bispecific CD19/CD22-targeting chimeric antigen receptor T cells." (PMID 38635232, 2024). "CD79 antibodies were previously developed to address autoimmunity, and CAR-T cells targeting CD22 have shown promise in pre-B cell Acute Lymphoblastic Leukemia." (PMID 34793513, 2021). "To prevent relapse with CD19− or CD19lo disease, we tested a bispecific CAR targeting CD19 and/or CD22 (CD19-22.BB.z-CAR) in a phase I clinical trial (NCT03233854) of adults with relapsed/refractory B cell acute lymphoblastic leukemia (B-ALL) and LBCL." (PMID 34312556, 2021). "CD22 is expressed by most blasts from the majority (60–90%) of B-cell acute lymphoblastic leukemia (B-ALL)." (PMID 32012891, 2020). "CD22 has been evaluated as a candidate target antigen mainly in B-cell acute lymphoblastic leukemia, but clinical trials including patients with refractory CD22+ NHL are ongoing (NCT02794961, NCT02315612)." (PMID 32670869, 2020). "Similarly, relapsed or refractory patients with pre-B-cell acute lymphoblastic leukemia treated with CD22-CAR-T therapy after CD19-CAR failure often experience relapse due to a reduction in CD22 expression despite the persistence of CD22-CAR cells." (PMID 40699720, 2025). "Clinically, the anti-CD22 monoclonal antibody SM03 has shown efficacy in Phase III trials by disrupting CD22-SHP1-mediated NF-κB suppression, restoring B cell responsiveness in malignancies, while CD22-targeted CAR-T therapy demonstrates potent activity against B-cell acute lymphoblastic leukemia." (PMID 41154604, 2025). "However, when the CD19 and CD22 dual‐target CAR‐T cells were utilized to treat B‐cell acute lymphoblastic leukemia, the tumor cells were still able to develop resistance to CAR‐T cell therapy by downregulating the expression of CD19 and CD22 antigens." (PMID 38456710, 2024).
B-cell acute lymphoblastic leukemia (continued). "Bispecific CAR T cells targeting CD19 and CD22 exhibit clinical activity and low toxicity in patients with large B cell lymphoma and B cell acute lymphoblastic leukemia, with relapses associated with loss of CD19 but not CD22." (PMID 34312556, 2021). "In a phase I open-label study targeting B-cell acute lymphoblastic leukemia, CRISPR/Cas9 technology was used to construct universal CD19/CD22 dual-targeted CAR T cells." (PMID 40873568, 2025).
non-Hodgkin lymphoma (38 papers, 2010 to 2025). Distinct from Hodgkin lymphoma both morphologically and biologically, non-Hodgkin lymphoma (NHL) is characterized by the absence of Reed-Sternberg cells, can occur at any age, and usually presents as a localized or generalized lymphadenopathy associated with fever and weight loss. "For instance, studies have showcased the safe and significant effectiveness of 131I-anti CD45, 131I-anti CD22, and I-Rituximab in treating non-Hodgkin's lymphoma." (PMID 38475902, 2024). "This agent was recently evaluated in a phase I clinical trial in conjunction with rituximab, gemcitabine, dexamethasone, and cisplatin in patients with refractory CD22+ non-Hodgkin’s lymphoma (NHL)." (PMID 29329556, 2018). "Among the few examples in the literature, the coinjection of anti-CD20 and anti-CD22 mAbs has already been clinically evaluated in the treatment of non-Hodgkin lymphomas." (PMID 21504579, 2011). "Epratuzumab, a humanized anti-CD22 monoclonal antibody, is under investigation as a therapeutic antibody in non-Hodgkin's lymphoma and systemic lupus erythematosus (SLE), but its mechanism of action on B-cells remains elusive." (PMID 21050432, 2010). "Anti-CD22 therapeutic antibodies have been developed in different forms, and an antibody called epratuzumab has been clinically studied in B cell malignancies, such as non-Hodgkin’s lymphoma and systemic lupus erythematosus." (PMID 37039643, 2023). "Therefore, the IT was further evaluated in a phase I trial (CTI: NCT00126646) on 46 CD22+ patients (four non-Hodgkin’s lymphoma (NHL), 11 chronic lymphocytic leukemia (CLL), and 31 HCL)." (PMID 34976821, 2021). "Coupling of the humanized anti-CD22 antibody targeting the lymphocyte marker CD22 to PEGylated doxorubicin-loaded liposomes increased doxorubicin accumulation in Non-Hodgkin's Lymphoma xenografts and increased survival over untargeted doxorubicin-loaded liposomes." (PMID 23533772, 2013). "Interestingly, an immunotherapeutic approach that targets CD22, epratuzumab, has proved efficacious in the treatment of non-Hodgkin lymphoma, and in the autoimmune diseases, systemic lupus erythematosus and primary Sjögren's syndrome." (PMID 21435232, 2011). "InO was also assessed previously as either a single agent or in combination with chemotherapy for the treatment of CD22+ B-cell non-Hodgkin lymphoma (NHL)." (PMID 30859374, 2019). "Since most non-Hodgkin lymphomas (NHL) and B-ALL leukemic cells express surface CD22, a large number of preclinical and phase 1 studies evaluated the safety, antitumor activity, pharmacokinetics, and pharmacodynamics of InO for CD22+ B-cell tumors." (PMID 32012891, 2020). "Chimeric anti-CD22 SM03 was subjected to Phase I dose-escalation clinical studies in years 2007 to 2008 to evaluate its safety, pharmacokinetic properties and biological effect in Chinese non-Hodgkin lymphoma patients." (PMID 24816427, 2014). "Clinical radioimmunotherapy using an 90Y-labeled anti-CD22 mAb or an 131I-labeled anti-CD20 mAb has been shown to yield high rates of overall responses and durable complete responses in relapsed/refractory Non-Hodgkin Lymphoma, when given as 2 injections separated by 2 and 8 weeks, respectively." (PMID 22879947, 2012). "Several clinical trials have explored CD19- and CD22-targeted CAR-T cells (NCT01044069 and NCT02315612), showing promising results in acute lymphoid leukemia (ALL), as well as CD19-targeted CAR-T cells in various non-Hodgkin lymphoma (NHL) subtypes." (PMID 38259840, 2023).
autoimmune disease (29 papers, 2009 to 2026). A disorder resulting from loss of function or tissue destruction of an organ or multiple organs, arising from humoral or cellular immune responses of the individual to their own tissue constituents. "Under pathological conditions, CD22 is involved in the control of autoimmune diseases and genetic variants of CD22 are related to the susceptibility of individuals to autoimmune diseases through a defect in B cell tolerance." (PMID 34276669, 2021). "CD22 is implicated in B cell survival and proliferation and in induction of B cell tolerance and control of susceptibility to autoimmune diseases." (PMID 32324805, 2020). "Consistent with this notion, CD22-deficient mice show signs of B cell hyperactivation and can develop autoimmune diseases, particularly when in combination with deficiency of another B-cell Siglec, Siglec-G." (PMID 32324805, 2020). "Genetic variants of CD22, or enzymes involved in the glycosylation of ligands of CD22 have been linked to susceptibility in human autoimmune diseases." (PMID 30323814, 2018). "As a B-cell-restricted antigen, CD22 is targeted in therapies against dysregulated B cells that cause autoimmune diseases and blood cancers." (PMID 28970495, 2017). "Furthermore, in experimental studies, it has been shown that a loss of CD22 leads to B cell hyperactivation, implicating dysfunction in the development of autoimmune diseases." (PMID 40862721, 2025). "Consequently, CD22 deficiencies, and genetic variants are associated with hyperactive B cells and have been implicated in autoimmune disease." (PMID 31019513, 2019). "As knockout mice, deficient for both inhibitory Co-receptors, CD22 and Siglec-G, show a progressive autoimmune disease upon aging with lupus-like symptoms, the question arose whether the ligand binding function of both Siglecs is important to prevent autoimmunity." (PMID 30559744, 2018). "In contrast to our findings, a reduction in CD22 expression on B cells has been mostly reported in several autoimmune diseases." (PMID 39435875, 2025). "Development of high-affinity sialomimetics for CD22 holds promise for potent Siglec-targeted therapeutics for autoimmune diseases, other immune system disorders, and for targeting immune cell cancers." (PMID 34065256, 2021). "CD22 is an important drug target for ameliorating autoimmune diseases and acute lymphoblastic leukemia." (PMID 33907270, 2021). "It is therefore important to evaluate the involvement of CD22-targeting agents in the activation of humoral immunity against transplanted grafts in the same manner as they are applied to the treatment of autoimmune diseases to effectively manage AMR." (PMID 34276669, 2021). "As CD22 expression is restricted to B cells it can serve as important target for immunotherapy of B cell mediated autoimmune diseases and B cell related lymphomas." (PMID 30559744, 2018). "There has been a significant interest in adopting CD22-targeted agents, such as Emab as therapies for autoimmune diseases, and in particular, for SLE." (PMID 30323814, 2018). "More studies are needed to assess the functional significance of different CD22 SNPs and their possible contribution to autoimmune disease." (PMID 30323814, 2018). "We also describe the role of CD22 in autoimmunity and the great potential for CD22-based immunotherapeutics for the treatment of autoimmune diseases such as systemic lupus erythematosus (SLE)." (PMID 30323814, 2018). "Given the role of CD22 in modulating both BCR and TLR signaling, targeting CD22 with Emab has also been explored as a therapy for autoimmune diseases, including SLE and pSS." (PMID 28506291, 2017). "It is currently unclear how the glycosylation patterns of CD22 are altered in B-cell-derived malignancies and autoimmune diseases." (PMID 28970495, 2017). "As a result, CD22 knockout mice have an increased incidence of autoimmune disease and hyperactive B cells." (PMID 28970495, 2017).